HNF1A (HNF1 homeobox A)
Diseases named in the same sentence as HNF1A in open-access papers (continued):
Sharing a sentence is not in itself a finding about the gene and the disease.
tumor (continued). "HNF1A knockdown resulted in a near complete elimination of metastatic lesions, with a significant decrease in overall metastatic tumor area from 6.08% in the shNTC livers to 0.06% in the shHNF1A livers." (PMID 40731412, 2025). "The livers from HNF1A overexpressing mice also weighed significantly more than LacZ livers, again indicating increased tumor burden." (PMID 40731412, 2025). "Expectedly, the livers from mice inoculated with HNF1A overexpressing cells had significantly increased metastatic tumor burden as compared to mice implanted with LacZ cells." (PMID 40731412, 2025). "An intrasplenic injection xenograft model was used to evaluate the impact of HNF1A knockdown and overexpression on metastatic tumor burden." (PMID 40731412, 2025). "Imaging of the harvested livers at the six-week endpoint revealed significantly increased tumor burden in the livers of mice implanted with HNF1A overexpressing cells." (PMID 40731412, 2025). "The main tumor susceptibility genes in CBC3T-1 cells included BARD1, KDR, FAT1, HNF1A, BRCA2, FANCA, and BRCA1." (PMID 37966669, 2024). "Here, we provide molecular characterization of different HAs obtained from the same patient, describing the effects of biallelic inactivation of HNF1A, as well as its role as a tumor suppressor." (PMID 39408812, 2024). "Morphological characteristics of the lesions were analyzed, as well as HA tumor cell beta-catenin, glutamine synthetase, and HNF-1α protein expression via immunohistochemistry (IHC)." (PMID 39408812, 2024). "Hepatocyte nuclear factor 1A (HNF1A) is involved in tumor cell proliferation and growth, and induces epithelial mesenchymal transition." (PMID 38443412, 2024). "Similar changes in HNF1A protein levels were observed in tumor sections from A549 and A549/PR xenografts." (PMID 38228910, 2024). "In NSCLC tumor tissue microarrays and cancer network databases, we found a positive correlation between HNF1A and SHH expression." (PMID 38228910, 2024). "Based on this evidence, it was proposed that HNF1A acts as a tumor suppressor whose biallelic inactivation can be responsible for the onset of liver tumors, phenotypically characterized by a marked steatosis." (PMID 39408812, 2024). "HNF4α, then, promoted HNF1α expression and the interleukin pathway and resulted in a tumor growth effect." (PMID 39768557, 2024). "On the other hand, HNF4A is also known as a major tumor suppressor, and its expression is tightly regulated by HNF1A." (PMID 35327967, 2022). "In that study, the knockdown of HNF1A in multiple PDAC cell lines resulted in tumor growth inhibition and apoptosis, accompanied by a reduction in stem cell markers." (PMID 35328643, 2022). "Accordingly, putative target genes of HNF1A were significantly enriched in FGFR4 high tumours of the ICGC cohort." (PMID 35963908, 2022). "Particularly, HNF1α and HNF4α are highly expressed in CRC tumors, the former is linked with tumor malignancy of CRC cells and the latter is considered as a critical risk factor for CRC." (PMID 36497071, 2022). "For example, HNF1A exerts its tumor-suppressive effect by forming a complex with lysine-specific demethylase 6A, encoded by the KDM6A gene, to inhibit the oncogenic pathway in a mouse acinar cell line." (PMID 35328643, 2022). "In contrast, HNF1A overexpression in PDAC cell lines promoted tumor growth, accompanied by the elevation of stem cell markers." (PMID 35328643, 2022). "It acts as a tumor suppressor in the liver, evidenced by the increased proliferation in HNF1A knockout (KO) hepatocytes." (PMID 35327967, 2022). "For example, HNF1A-AS1 binds to the C-terminal of Src homology region 2 (SH2) domain-containing phosphatase 1 (SHP-1) protein and increases the phosphatase activity of SHP-1, which subsequently promotes anti-tumor effects of HNF-1α and HNF1A-AS1." (PMID 33808647, 2021). "Downregulation of HNF1A is observed in the tumor vs. normal pancreas, suggesting that decreased HNF1α levels are important for PDAC tumor progression." (PMID 34888306, 2021).
tumor (continued). "Tumor growth was inhibited by knockdown of HNF1A, and anticancer drug treatment further reduced tumor progression." (PMID 33990627, 2021). "Both HNF1α and HNF4α act as tumor suppressors, and they reduce expression of factors that can trigger tumor development in several types of cells." (PMID 34771521, 2021). "Loss of protein expression in malignant ductal cells of the pancreas suggested tumour suppressive roles of HNF1A/B in pancreatic cancer." (PMID 33580750, 2021). "The median HNF1A expression in the normal mucosa was 2.08 (range 0–89.38) and 2.89 (range 0–384.72) in tumor tissue, and it was higher in tumors than in normal mucosa (P = 0.001)." (PMID 33990627, 2021). "Hepatocyte nuclear factor 1-alpha (HNF1A) is involved in regulation of tumor cell proliferation, apoptosis, cycle distribution, invasion metastasis and chemical resistance." (PMID 34234870, 2021). "In six pairs of tumor/adjacent normal tissue sections showed positive HNF1A expression in healthy acinar clusters, diminished in ADM, but increased ectopically in ductal cancer cells." (PMID 32552862, 2020). "The function of HNF1A, however, is cell‐type specific, and both co‐expression network analysis of PDAC samples and in vitro studies suggest that HNF1A has a tumor‐suppressive function in pancreatic exocrine cells." (PMID 32154941, 2020). "EMT markers Snail and N-Cadherin were both downregulated in the HNF1α-silenced AsPC-1 xenograft tumor tissues compared to the control experimental group." (PMID 33214606, 2020). "Further, we examined effect of HNF1α on proliferation, EMT, and apoptosis markers using xenograft tumor tissues from HNF1α silenced AsPC-1 and control xenograft tumor tissues." (PMID 33214606, 2020). "Further, it has also been demonstrated that HNF1α is required for tumor growth, tumorsphere formation, invasion and migration." (PMID 33214606, 2020). "Further, the dataset also showed the differential expression of HNF1α at different PDAC tumor grades." (PMID 33214606, 2020). "HNF1A, ESR1, and FLT4 were mutated significantly more frequently in tumor tissue samples obtained from patients with stage III BC, while SYNE1, PER1, and LRP1B were mutated significantly more frequently in stage IV BC." (PMID 32731384, 2020). "The mutations are biallelic in most cases of HCA, which is consistent with the role of HNF1A as a tumor suppressor." (PMID 31754975, 2020). "A more fine-grained analysis would benefit from a global, i.e., whole tumor quantitative analysis of KRT81 and HNF1a expression, which is currently unfeasible due to the necessity of whole tumor work-up." (PMID 32155990, 2020). "Analysis of expression of HNF1α in PDAC based on tumor grade indicates that early stage disease has higher expression and as the disease progresses the expression decreases." (PMID 33214606, 2020). "We identify miR-484 as a metastasis specific suppressor with hypermethylation of promoter in CC and reveal a novel pathway in which DNMT1 epigenetically mediates miR-484 repression with resultant MMP14/HNF1A activation, which results in tumor metastasis in CC." (PMID 31810492, 2019). "We found that MMP14 and HNF1A were upregulated in cancer tissues compared with the adjacent non-tumor tissues." (PMID 31810492, 2019). "Muckenhuber and colleagues suggest KRT81+ tumor cells to be more resistant to the FOLFIRINOX regimen compared to the exocrine-like subtype (HNF1A+)." (PMID 31191661, 2019). "Since knockdown of HNF4A caused a reduction in ApoB and HNF1A expression, possibly loss of HNF4 reduces the expression of these genes and subsequently tumor growth is triggered." (PMID 29899848, 2018). "Depletion of HNF1A effectively inhibited PDA cell growth, tumorsphere formation, and tumor growth, with a loss of PCSC marker expression observed both in vitro and in vivo." (PMID 30074477, 2018). "HNF1A-depleted cells showed significantly reduced tumor growth compared to their control cohorts (p<0.05)." (PMID 30074477, 2018).
tumor (continued). "Most importantly, intratumoral HNF1α transduction significantly inhibits tumor growth in mice and eradicates HCC nodules after systemic delivery." (PMID 28943628, 2015). "The mean (± SD) intensity of the HNF1A band after normalized to that of the β-actin was significantly lower in tumor (0.71 ± 0.11) than those in non-tumor tissues (0.80 ± 0.13) (p = 0.005, paired t test)." (PMID 25793983, 2015). "HNF1A mRNA expression were detected by qRT-PCR in 27 paired resected pancreatic adenocarcinoma tumor tissues and their adjacent non-tumor tissues." (PMID 25793983, 2015). "Extensive evidence suggested that HNF1α acts as a tumor suppressor gene and that its down-regulation contributes to the development of HCC." (PMID 28943628, 2015). "By Western blot, we found a lower level of HNF1A protein in 7/8 (87.5%) of the tumors compared to their adjacent non-tumor tissues." (PMID 25793983, 2015). "Previously, the HNF1A/MIA2 secretory axis has been demonstrated to have a tumor suppressor function in HCC13." (PMID 25657029, 2015). "Immunohistochemistry revealed that the level of HNF1A expression was significantly lower in tumor tissues than in non-tumor tissues." (PMID 25793983, 2015). "The level of HNF1A expression was significantly lower in tumor than those in non-tumor tissues (p = 0.005, paired t test)." (PMID 25793983, 2015). "The mean level of HNF1A mRNA expression in tumor tissues was reduced to 44.4% of that in non-tumor tissues, although three out of the 27 pairs showed a higher level of HNF1A expression in the tumors." (PMID 25793983, 2015). "The tumor suppressor role of HNF1A is also supported by findings from the gene knockdown experiments." (PMID 25793983, 2015). "We further showed that the homogeneous accumulation of lipids in tumor hepatocytes was related to an increase of fatty acid synthesis induced by HNF1A inactivation." (PMID 23401783, 2013). "We further showed that HNF1A inactivation induces in hepatocyte dramatic alteration in metabolic pathways and epithelial-mesenchymal transition that can participate to tumor development." (PMID 23401783, 2013). "HNF1A is highly expressed in PCa cells, and its knockdown can suppress tumor growth." (PMID 41583511, 2026). "Collectively, these findings suggested that HNF1A may act as a co-regulator of the tumor-suppressive effects of MAOB." (PMID 41338163, 2025). "Other groups have previously proposed tumor suppressive functions for both HNF1A and FGFR4." (PMID 40731412, 2025). "HNF families, including HNF1A, are involved in liver development, function, and tumor growth." (PMID 35328643, 2022). "Recent data from many studies have established HNF1α as a tumor suppressor." (PMID 34771521, 2021). "Knockdown of HNF1A increased tumor reduction by oxaliplatin." (PMID 33990627, 2021). "Biological assessments showed that HNF1A expression is related to tumor malignancy of CRC cells." (PMID 33990627, 2021). "Knockdown of HNF1A significantly increased apoptotic cells in anti-tumor drug treatment." (PMID 33990627, 2021). "Moreover, through miR-150-5p and miR-504, Linc00673 can regulate the expression of ZEB1 14 and HNF1A 16, respectively, and then exert tumor-promoting or anti-tumor activity." (PMID 33390809, 2021). "From these results, it was notable that HNF1A strongly related anti-tumor drug sensitivity." (PMID 33990627, 2021). "By silencing HNF1α, tumor growth was reduced in xenografts when compared to control tumors." (PMID 33214606, 2020). "This suggested that Kdm6a could exert its tumor suppressor function through broadly similar pathways as Hnf1a, namely through the maintenance of acinar differentiated cell programs and inhibition of growth‐promoting pathways." (PMID 32154941, 2020). "Further, it also confirmed the differential expression of HNF1α at different tumor grades." (PMID 33214606, 2020).
tumor (continued). "The analysis of molecular signatures in human tumors, and the semblance of mouse genetic phenotypes, suggested that KDM6A and HNF1A might control common tumor‐suppressive programs in pancreatic exocrine cells." (PMID 32154941, 2020). "Previous studies in other human cancers have suggested a tumor suppressor role of the HNF1A gene." (PMID 31810492, 2019). "Importantly, western blot analysis of resultant tumor lysates confirmed that shRNAs remained effective at depleting HNF1A during the course of the experiment." (PMID 30074477, 2018). "Still, a tumor suppressive role for HNF1A in PDA has also been proposed." (PMID 30074477, 2018). "Importantly, depletion of HNF1A in xenografts impaired tumor growth and depleted PCSC marker-positive cells in vivo." (PMID 30074477, 2018). "Knockdown of HNF1A impairs tumor growth and depletes CSCs in vivo." (PMID 30074477, 2018). "Taken together, these findings suggested that restoration of HNF1α functions in HCC could restrain tumor proliferation and progression." (PMID 28943628, 2015). "Expression of HNF1A, pAKT, pmTOR in paired tumor and normal pancreatic tissues." (PMID 25793983, 2015). "Previous studies in other human cancers have suggested a tumor suppressor role of HNF1A gene." (PMID 25793983, 2015). "supporting a tumor suppressor role of HNF1A in the development of human cancers." (PMID 25793983, 2015). "Recently, the role in tumor suppression of HNF1α and HNF6, has been described." (PMID 28943628, 2015). "However, HNF1A has also been noted to have tumor-suppressive roles in certain contexts." (PMID 41583511, 2026). "In addition, the analysis of PCa tissue samples revealed that elevated HNF1A expression was significantly correlated with higher pathological Gleason scores, larger tumor sizes, and tumor metastasis, as well as enrichment of pathways related to MYC and E2F targets." (PMID 41583511, 2026). "We have also previously shown that HNF1A may be a tumor suppressor gene in the pancreas." (PMID 29422604, 2018). "Single-cell analysis identified a previously unrecognized hepatic-differentiated tumor subpopulation expressing master transcription factors HNF1A and HNF4A, which was positioned at the terminal stages of tumor evolution." (PMID 41981779, 2026). "Our study demonstrates that in ccRCC, S100A2 functions as a cofactor assisting the transcription factor HNF1A in promoting GLUT2 expression, thereby enhancing glycolysis and driving tumor progression." (PMID 40011447, 2025). "On the other hand, we report the somatic mutational landscape of HCC in our cohort, identified exclusively in the tumor tissues, with APC (100%), ALK (94%), HNF1A (56%), CDKN2A and HRAS (50%) emerging as the most frequently mutated genes." (PMID 41567639, 2025). "The increase in HNF1A and HNF4G protein after enzalutamide treatment was also observed by IHC of tumor samples." (PMID 40553565, 2025). "We found that expression of HNF1A and FGFR4 were significantly higher in PDAC cell lines of a metastatic/ascites origin versus primary tumor origin." (PMID 40731412, 2025). "In the progression of liver cancer,HNF4α is regulated by factors such as STAT3 and KAT2B, and function as tumor suppressor through HSD17B6, HNF1α, FOXAs, MARC2." (PMID 36249028, 2022). "For HNF4α-based targeting therapeutics in HCC, HNF4α and HNF1α have been used to inhibit HCC cell proliferation and eliminate tumor-specific features." (PMID 36249028, 2022). "As a summary, Calderaro and colleagues identified β-catenin-activated HCA as potentially related to malignant transformation and found common metabolic defects in HCA inactivated for HNF1A and in GSD non-tumor livers." (PMID 33922238, 2021).
tumor (continued). "Mechanistically, METTL3 regulated the expression of the HNF1 homeobox A (HNF1A) in a METTL3-m6A-IGF2BP2-dependent manner, eventually enhancing the migratory ability of tumor cells and activating the Wnt pathway." (PMID 33879256, 2021). "We further provide epigenomic, biochemical, and genetic evidence that mechanistically link HNF1A function in pancreatic exocrine cells to KDM6A, an established tumor suppressor." (PMID 32154941, 2020). "The current HCA classification scheme is based on the tumor’s morphologic and immunohistochemical characteristics and was originally validated with CTNNB1 and HNF1A gene sequencing." (PMID 26961851, 2016). "In functional studies, HNF1A overexpression transformed non-tumorigenic pancreatic cells and knockdown of HNF1A significantly depleted tumor growth in a patient-derived xenograft model." (PMID 40731412, 2025). "Specific genes downregulated in HG tumours which showed significantly higher promoter methylation included the developmental transcription factors CDX1, CDX2, GATA6, HNF1A, the marker of colonic differentiation, DPP4, and the markers of LGR5+ intestinal stem cells, ASCL2, LGR5." (PMID 40473896, 2025). "In contrast, luminal A/B tumor cells and LM cells showed high accessibility for the ER ESR1, as well as forkhead proteins, including FOXA2 and FOXP1, GATA3 and other GATA-box TFs, and HNF1A." (PMID 39478117, 2024). "In addition, multiple hepatocyte nuclear factors (e.g., HNF1A, HNF4A, and HNF4G) we identified in tumor cells have been shown to be specific for proximal tubule cells, which are the original cells of ccRCC79." (PMID 35853872, 2022). "Again, we found no systematic differential expression of HNF1A between the tumor and matched normal tissues." (PMID 35227282, 2022). "HNF1A positivity in cancer was consistent with the cancer persister cells, which were not eliminated from the tumor during gemcitabine chemotherapy." (PMID 32552862, 2020). "Therefore, miR-484 regulated cell adhesion and tumor growth through both directly targeting MMP14 and HNF1A." (PMID 31810492, 2019). "Thus, miR-484, who is downregulated by DNMT1-mediated hypermethylation in its promoter, functions as a tumor suppressor by inhibiting MMP14 and HNF1A expression in CC." (PMID 31810492, 2019). "The immunohistochemical examination revealed that the tumor cells matched neither the HNF-1α-inactivated subtype (due to the presence of fatty acid-binding protein) nor the β-catenin-activated subtype (due to the absence of β-catenin and glutamine synthetase)." (PMID 31410698, 2019). "Taken together, these observations suggest that HNF1A and HNF1B can be co-expressed in normal pancreatic tissues and may act as tumor suppressors through their regulatory activity." (PMID 27520560, 2016). "Next, Western blot were conducted in eight pairs of tumor and non-tumor tissues to examine HNF1A expression at the protein level." (PMID 25793983, 2015). "Altogether, our results demonstrate a new level of control of HNF1α by TGFβ that can represent the first event in triggering EMT process in hepatocyte and disclose a potential limitation to the use of an exogenous molecule as therapeutic MET inducer and tumor suppressor tool." (PMID 31543815, 2019). "This expression profile was very similar to that observed in HNF1A-inactivated HCA but markedly different from that in steatotic and non-steatotic non-tumor liver tissues." (PMID 33922238, 2021).